VGF (VGF nerve growth factor inducible)
Description:
[Neurosecretory protein VGF]: Secreted polyprotein that is packaged and proteolytically processed by prohormone convertases PCSK1 and PCSK2 in a cell-type-specific manner (By similarity). VGF and peptides derived from its processing play many roles in neurogenesis and neuroplasticity associated with learning, memory, depression and chronic pain (By similarity). [Neuroendocrine regulatory peptide-1]: Plays a role in the control of body fluid homeostasis by regulating vasopressin release. Suppresses presynaptic glutamatergic neurons connected to vasopressin neurons. [Neuroendocrine regulatory peptide-2]: Plays a role in the control of body fluid homeostasis by regulating vasopressin release. Activates GABAergic interneurons which are inhibitory neurons of the nervous system and thereby suppresses presynaptic glutamatergic neurons (By similarity). Also stimulates feeding behavior in an orexin-dependent manner in the hypothalamus (By similarity). Functions as a positive regulator for the activation of orexin neurons resulting in elevated gastric acid secretion and gastric emptying (By similarity). [VGF-derived peptide TLQP-21]: Secreted multifunctional neuropeptide that binds to different cell receptors and thereby plays multiple physiological roles including modulation of energy expenditure, pain, response to stress, gastric regulation, glucose homeostasis as well as lipolysis (By similarity). Activates the G-protein-coupled receptor C3AR1 via a folding-upon-binding mechanism leading to enhanced lipolysis in adipocytes (By similarity). Interacts with C1QBP receptor in macrophages and microglia causing increased levels of intracellular calcium and hypersensitivity (By similarity). [VGF-derived peptide TLQP-62]: Plays a role in the regulation of memory formation and depression-related behaviors potentially by influencing synaptic plasticity and neurogenesis. Induces acute and transient activation of the NTRK2/TRKB receptor and subsequent CREB phosphorylation (By similarity). Also induces insulin secretion in insulinoma cells by increasing intracellular calcium mobilization (By similarity). [Antimicrobial peptide VGF[554-577]]: Has bactericidal activity against M.luteus, and antifungal activity against P. Pastoris.
Synonyms: SCG7; SgVII
Tractability: Antibody: UniProt places it where antibodies can reach, with high confidence; UniProt predicts a signal peptide or a membrane-spanning region; its Gene Ontology location is reachable by antibodies, with medium confidence. PROTAC: its protein half-life has been measured.
Gene: Protein-coding gene on chromosome 7 (101,162,509 to 101,167,227, reverse strand). Ensembl gene ENSG00000128564.
Subcellular location: Secreted (Neurosecretory protein VGF); Cytoplasmic vesicle, secretory vesicle
Subcellular location (Human Protein Atlas): Golgi apparatus; Vesicles; Predicted to be secreted
Pathways (Reactome):
Metabolism of proteins: Post-translational protein phosphorylation; Regulation of Insulin-like Growth Factor (IGF) transport and uptake by Insulin-like Growth Factor Binding Proteins (IGFBPs)
Signal Transduction: NGF-stimulated transcription
Gene Ontology:
Molecular function: hormone activity; neuropeptide hormone activity
Biological process: response to cAMP; carbohydrate homeostasis; regulation of synaptic plasticity; signal transduction
Cellular component: cytoplasmic vesicle; extracellular region; Golgi apparatus; endoplasmic reticulum lumen; transport vesicle
Genetic constraint (gnomAD): Loss-of-function variants: 13 observed, 23.91 expected, observed/expected ratio (o/e) 0.54, 90% interval 0.35 to 0.86. The synonymous counts are far from expectation, so gnomAD's model fits this gene poorly and the ratio says little. Missense variants: 909 observed, 725.25 expected, observed/expected ratio (o/e) 1.25, 90% interval 1.19 to 1.32. Synonymous variants: 466 observed, 339.72 expected, observed/expected ratio (o/e) 1.37, 90% interval 1.27 to 1.48.
Homologues: Orthologues: macaque VGF (99% identical), dog VGF (93% identical), rat Vgf (87% identical), mouse Vgf (87% identical), pig VGF (79% identical), guinea pig VGF (74% identical).
Diseases named in the same sentence as VGF in open-access papers:
VGF is named in the same sentence as 95 diseases in open-access papers, as found by Europe PMC text mining. Sharing a sentence is not in itself a finding about the gene and the disease. The quoted sentences say what the papers report.
Alzheimer disease (28 papers, 2011 to 2025). A progressive, neurodegenerative disease characterized by loss of function and death of nerve cells in several areas of the brain leading to loss of cognitive function such as memory and language. "Dual specificity protein phosphatase 6 (DUSP6) was recently identified as a key hub gene in a causal VGF gene network that regulates late-onset Alzheimer’s disease (AD)." (PMID 39006222, 2024). "High levels of VGF are protective against the development of Alzheimer’s disease generally, and on an APOE E4 risk background there is approximately a 50% reduction in the proportion of individuals with LOAD when there are high levels of VGF (yellow box)." (PMID 38168398, 2023). "Apart from depression, Alzheimer’s disease (AD), and other neuroendocrine diseases, VGF has been associated with cancer." (PMID 37742030, 2023). "Both NPTXR and VGF were found to be significantly different in a CSF of presymptomatic persons with familiar Alzheimer’s disease due to PSEN1 and APP mutations as compared to related non carriers by high resolution LC-MS." (PMID 26270474, 2015). "Changes in the expression of VGF in the brain or CSF are associated with schizophrenia, depressive disorders, Parkinson's and Alzheimer's disease." (PMID 25013207, 2014). "In Alzheimer’s disease (AD) brain, significant decreases in VGF neuropeptides in the CSF (cerebrospinal fluid) have been found to be associated with cognitive decline." (PMID 41409785, 2025). "Available data for VGF reports decreased levels in dementia with Lewy bodies, amyotrophic lateral sclerosis, Alzheimer’s disease, and brain tissue of PD subjects." (PMID 38760408, 2024). "These include a VGF-centered Alzheimer’s disease network, where the majority of genes regulate neuronal activity, synaptic plasticity, and cognitive function or genes associated with age-related cognitive decline." (PMID 31396031, 2019). "Secretion of VGF is increased in cerebrospinal fluid and blood in neurodegenerative disorders like Alzheimer's disease (AD) and VGF is a potential biomarker for these disorders." (PMID 26142708, 2015). "The 4.82-kDa neurosecretory protein VGF peptide was found to be downregulated in Alzheimer's disease, while the 3.69-kDa neurosecretory protein VGF peptide was reported to be decreased in frontotemporal dementia." (PMID 25256248, 2015). "Decreased VGF content in the CSF has also been described in Alzheimer’ disease and frontotemporal dementia." (PMID 22970211, 2012). "Reduced CHGA (as well as VGF and cystatin C) levels were found in a proteomic analysis of CSF of patients with Alzheimer’s disease." (PMID 22970211, 2012). "VGF4.8 and other similar VGF peptides have been reported in Alzheimer's disease, amyotrophic lateral sclerosis (ALS), and frontotemporal dementia." (PMID 21838886, 2011). "Indeed, several animal studies have shown that forced expression of VGF gene and VGF-derived peptides attenuate Alzheimer’s disease (AD)-related phenotypes." (PMID 35203704, 2022). "Importantly, DUSP4 gene expression, like that of VGF, is downregulated in postmortem Alzheimer’s disease (AD) brains." (PMID 36497141, 2022). "In recent studies, reduced cerebrospinal fluid (CSF) levels or brain expression of VGF, Scg2, CgB, and CgA proteins have been reported in patients with Alzheimer’s disease (AD), with an estimated decrease in CSF VGF levels at a rate of 10.9% per year in a longitudinal study of patients with AD." (PMID 34238925, 2021). "Furthermore, VGF has been suggested as a biomarker in CSF for Alzheimer’s disease (AD) and Amyotrophic lateral sclerosis (ALS) and its expression was reduced in the CSF of AD and ALS patients compared to controls." (PMID 33481347, 2021). "Interestingly, miR-132, VGF, and PHFtau-tangles are reported to be dysregulated in brains of both Alzheimer’s dementia and PD patients." (PMID 31582723, 2019).
Alzheimer disease (continued). "Therefore, some VGF fragments were considered as biomarkers for neurological and psychiatric disorders, such as Alzheimer's disease, frontotemporal dementia and schizophrenia." (PMID 25013207, 2014). "Additionally, six VGF neuropeptides were linked to cognition independent of pathology, providing insights into Alzheimer's disease molecular underpinnings." (PMID 40334744, 2025).
depression (28 papers, 2010 to 2024). "VGF and peptides derived from its processing play many roles in neurogenesis and neuroplasticity associated with learning, memory, depression, and chronic pain." (PMID 37266401, 2023). "Beyond the report of inactivation of VGF in cancer by our group, it was also reported by other groups as a gene associated with different pathologic conditions; such as mutation of VGF in mice produced depression and homozygous VGF-null mice were small, hypermetabolic, hyperactive, and infertile." (PMID 24830820, 2014). "A transcriptome analysis showed that PAS840 upregulated the BDNF/VGF/NGFR pathway and increased neurotrophic nutrition to promote neurological function recovery and attenuate the risk of IS-induced depression." (PMID 39679371, 2024). "High-throughput sequencing of RNA transcriptome showed that CDYL can affect synaptic plasticity by transcriptionally inhibiting the expression of neuropeptide VGF, thereby regulating the occurrence and development of stress-mediated depression." (PMID 38331935, 2024). "In animal studies, dysregulation of VGF had effect on brain development and behavioral phenotypes, depression-like behaviors, and memory consolidation and stress resilience." (PMID 36617561, 2023). "VGF is an exercise regulated protein that is downregulated by stress and models of depression, and upregulated with exercise." (PMID 35546951, 2022). "Brain-derived neurotrophic factor (BDNF), vascular endothelial growth factor (VEGF), fibroblast growth factors (FGF) and VGF nerve growth factor are all involved in the pathophysiology of depression and are modulated by antidepressants." (PMID 33255237, 2020). "VGF nerve growth factor concentrations have been found to be altered in depression, normalizing after antidepressant therapy, but only in clinical responders." (PMID 33255237, 2020). "VGF serum levels are significantly lower in patients with major depressive disorder compared to controls and were reversed by 8 weeks of drug treatment with anti-depressants." (PMID 31058853, 2019). "Recent studies, in fact, have highlighted a possible role for VGF-derived peptides in depression and neuropsychiatric disorders, for which social stress is a known key-player." (PMID 31878142, 2019). "Patients with depression and bipolar disorder have lower-than-normal levels of VGF, whereas patients with schizophrenia and other cohorts of patients with depression have higher-than-normal levels." (PMID 28680036, 2017). "Increasing evidence suggests that VGF has a critical role in depression, so that it can induce antidepressant like properties in animal models." (PMID 29552054, 2017). "Patients with depression and bipolar disorder express lower levels of VGF, while patients with schizophrenia and other cohorts of patients with depression express higher levels of VGF20–22." (PMID 28680036, 2017). "VGF protein expression is reduced in both the learned helplessness and forced swim test depression paradigms, while VGF is increased by antidepressant drugs and voluntary exercise." (PMID 25699015, 2015). "VGF is upregulated by both BDNF and 5-HT treatment, and VGF protein in the hippocampus is reduced in animals subjected to behavioral models of depression." (PMID 25542689, 2014). "Taken together, these studies suggest an important role for VGF and VGF-derived peptides as critical mediators of memory and depression-like behavior, and that novel VGF therapeutics may provide new approaches to MDD." (PMID 35909451, 2022). "In conclusion, the present study demonstrates that VGF-overexpressing mice exhibit behavioral and morphological abnormalities that may be related to the mental illnesses such as schizophrenia and depression." (PMID 28680036, 2017). "Therefore, a damaged serotonin signal may reduce VGF expression in patients with suicidal depression." (PMID 32398015, 2020).
depression (continued). "Additionally, it is important to clarify whether the abnormal behaviors of VGF-overexpressing mice are related to schizophrenia or/and depression by evaluating the efficacy of therapeutic drugs for these illnesses." (PMID 28680036, 2017). "The evidence presented in this review indicates that the gene and gene product have a key neuroendocrine role and that VGF or its derived peptides may act as biomarkers or therapeutic targets in a number of disorders such as obesity, dementia, depression, and pain." (PMID 25699015, 2015). "As NPY and VGF also actively participate in the neurotrophic hypothesis of depression and could be regulated by BDNF, our data argue that both BDNF and its downstream neurotrophic peptides, NPY and VGF, may play a role in the antidepressant effects of exercise." (PMID 25477997, 2014). "Crocus sativus L. (Saffron), as one of the most clinically effective herbal extracts, has shown antidepressant effects in various experimental depression models by modulating the BDNF, cyclic AMP response element binding protein (CREB), and VGF pathways." (PMID 37047914, 2023). "An increasing number of studies have demonstrated that BDNF and VGF (nonacryonimic) proteins are decreased in animal models of depression." (PMID 36550125, 2022). "Brain-derived neurotrophic factor (BDNF) and TrkB play crucial roles in cognition, memory, and depression, driven at least in part by downstream effectors, including VGF (non-acronymic)." (PMID 35909451, 2022). "Our results demonstrate that repeated rapastinel injection could alleviate depression-like behaviors similar with ketamine binding to NMDAR, which further activated the VGF/BDNF/TrkB/ERK pathway, thereby regulating protein translation (e.g., VGF and BDNF)." (PMID 36550125, 2022). "Thirdly, to highlight the specificity of our findings in patients with suicidal depression, we only tested VGF levels; we did not detect other neurotrophic factors that have been associated with suicide risk." (PMID 32398015, 2020). "Correlation analysis showed that the level of serum VGF was negatively correlated with risk of suicide in patients with MDD (r = − 0.55, p = 0.001), but not with the severity of depression (HDRS score) (r = − 0.15, p = 0.11)." (PMID 32398015, 2020). "First, the results presented by Bartolomucci and coworkers appear somehow in contrast with other observations showing that the lack of VGF gene, and therefore assuming the absence of VGF-derived peptides, increased depression-related behavioral changes." (PMID 31878142, 2019). "Several lines of evidence confirm that neuropeptide VGF (nonacronymic) can be induced by both nerve growth factor and neurotrophic factor and may act against depression by regulating the proliferation and survival of neurons." (PMID 32398015, 2020). "However, the roles of VGF in depression barely begin to be studied, being evident the lack of knowledge around this neuropeptide." (PMID 22654714, 2011). "The neurotrophic hypothesis of depression is based on the stress-induced downregulation and rapid-acting antidepressant-induced upregulation of BDNF and neuropeptide VGF (nonacronymic) expression in the brain." (PMID 25542689, 2014). "VGF (nonacryonimic) and phosphatidylinositol 3-kinase (PI3K)/AKT (also known as protein kinase B, PKB)/mammalian target of rapamycin (mTOR) signaling play pivotal roles in depression." (PMID 25542689, 2014).
amyotrophic lateral sclerosis (12 papers, 2011 to 2025). Amyotrophic lateral sclerosis (ALS) is a neurodegenerative disease characterized by progressive muscular paralysis reflecting degeneration of motor neurons in the primary motor cortex, corticospinal tracts, brainstem and spinal cord. "VGF mRNA is widely expressed in areas of the nervous system known to degenerate in Amyotrophic Lateral Sclerosis (ALS), including cerebral cortex, brainstem and spinal cord." (PMID 27737014, 2016). "AQEE-30 is one of the VGF peptides, which are derived from the VGF polypeptide precursor, and related to various physiological phenomena including neuroprotective effects in Huntington′s disease and amyotrophic lateral sclerosis (ALS)." (PMID 36430431, 2022). "VGF expression is reduced in the brains of patients with neurodegenerative disease, including AD, Parkinson’s disease, and amyotrophic lateral sclerosis (ALS)." (PMID 31924226, 2020). "VGF is a peptide present in the CNS and PNS that protects motor neurons in animal models of amyotrophic lateral sclerosis and increases the survival of cerebellar granule cells after serum deprivation." (PMID 25290916, 2014).
dementia (12 papers, 2011 to 2025). Loss of intellectual abilities interfering with an individual's social and occupational functions. "VGF has been reliably implicated in well powered multi-omic AD studies, with CSF10,43,51,52 and cortical depletion of VGF associated with AD and other dementia-types." (PMID 38531951, 2024). "In similar situations, such as ALS and frontolateral dementia, progression of neuronal damage probably causes a decrease of neuronal products of VGF and loss of their protective function." (PMID 21838886, 2011). "In addition, the next-generation RNA sequencing of cingulate cortex samples (from 23 PD patients, compared with 11 controls) found the VGF gene to be implicated in the molecular etiology of PD and PD-related dementia." (PMID 37446110, 2023). "Meanwhile, both dementia groups featured starkly decreased levels of known neuroprotective markers VGF and NPTX2, which are consistently decreased in the brains of those with neurodegeneration." (PMID 39107789, 2024). "All 17 proteoforms were increased in resilience, compared to dementia, with seven peptides derived from VGF." (PMID 38531951, 2024). "VGF levels were also reduced in patients with MCI only in those who then progressed to AD, further indicating the potential role of VGF as a biomarker in dementia." (PMID 35909451, 2022). "For example, VGF levels in cerebrospinal fluid (CSF) were lower in dementia with Lewy bodies compared to AD and healthy controls." (PMID 32192109, 2020). "Previous studies have shown an association of lower levels of in NPTX2 and VGF with worse cognition in non-demented individuals with AD and conversion to dementia." (PMID 40033427, 2025). "Likewise, Venn analysis of downregulated genes identified 3 genes, dual specificity phosphatase 6 (DUSP6), VGF nerve growth factor inducible (VGF), and activity regulated cytoskeleton associated protein (ARC) shared between dementia types." (PMID 32192109, 2020). "For example, VGF peptides cleaved at the N-terminus of proVGF were found to be altered in CSF of psychiatric disorders, while others in the middle of proVGF may be useful CSF biomarkers for dementia." (PMID 37446110, 2023). "Seven proteoforms of VGF (non-acronymic) were repeatedly significantly enriched in resilient vs dementia brain." (PMID 38531951, 2024).